NOTCH2 (notch receptor 2)
Diseases named in the same sentence as NOTCH2 in open-access papers (continued):
Sharing a sentence is not in itself a finding about the gene and the disease.
colorectal cancer (26 papers, 2011 to 2025). A primary or metastatic malignant neoplasm that affects the colon or rectum. "Similarly, loss of miR-449a was found to promote colon carcinogenesis, again linked to NOTCH activity, and miR-195-5p regulates NOTCH2 expression in colorectal cancer." (PMID 33430387, 2021). "For example, in colorectal cancer, NOTCH2 expression was shown to enhance GATA3-mediated IL-4 secretion, directly promoting M2-type TAM polarization." (PMID 41200204, 2025). "For instance, miR-195-5p regulated Notch2-mediated tumor cell EMT by directly binding to the 3’-UTR of the Notch2 mRNA in colorectal cancer." (PMID 36153332, 2022). "We examined the genotypes of four germline SNPs residing in NOTCH1 - rs3124591, NOTCH2 - rs11249433, NOTCH3 - rs1043994, and NOTCH4 - rs3830041 to determine their association with breast and colorectal cancer risk in Saudi Arabian patients." (PMID 34257585, 2021). "In the present study, we evaluated for the first time the association of NOTCH1, rs3124591; NOTCH2, rs11249433; NOTCH3, rs1043994, and NOTCH4, rs3830041 SNPs with the susceptibility of breast and colorectal cancers in Saudi population." (PMID 34257585, 2021). "The region of gain of chromosome 1p included the colorectal cancer-associated genes REG4 and NOTCH2 and gain of 15q included the genes MAP2K1, SMAD3, SMAD6, and IGF1R, among others." (PMID 31620944, 2019). "Previous studies showed differential expression profiling of Notch1 and Notch2 in colorectal carcinoma specimens, which revealed up-regulation of Notch1 and down-regulation of Notch2 with significant relations to tumor differentiation status." (PMID 30988066, 2019). "Genes of Notch signaling pathway such as Notch1, Notch2, HES1, DLL1, and JAG1 have been reported to be associated with the pathological tumor characteristics and degree of differentiation in colorectal cancer." (PMID 29100272, 2017). "Additionally, posttranscriptional regulation of NOTCH2 through miR-195-5p in colorectal cancer leads to a significant reduction of NOTCH2 protein, and subsequently to a lowered EMT profile." (PMID 33430387, 2021). "Notch-1 and Notch-2 function in opposite ways in colorectal cancer." (PMID 31198409, 2019). "Similarly, Notch1 and Notch2 have been reported to have opposite prognostic effects in patients with colorectal cancer." (PMID 29963552, 2018). "Accordingly, Jagged1 expressing EC- tumor cell signaling has been described in the regulation of colorectal cancer, and in the ability of providing chemo resistance, aggressiveness to lymphoma cells by activating Notch2 and consequently Hey1 in these adjacent cells." (PMID 26213336, 2015). "In order to evaluate whether gender played any role in the association of NOTCH1-rs3124591, NOTCH2-rs11249433, NOTCH3-rs1043994, and NOTCH4-rs3830041 with colorectal cancers, the study subjects were grouped as males and females for counting the genotype and allele frequencies." (PMID 34257585, 2021). "In this cohort, data supported the antagonistic roles of NOTCH1 and NOTCH2 in phenotypes of colorectal cancer cells, where NOTCH1 acted as an oncogenic enhancer whereas NOTCH2 played a tumor suppressor role." (PMID 37860822, 2023). "In colorectal cancer patients, the overexpression of LEF1 represented a risk factor for the poor overall survival of CRC patients, and increased expression of LEF1 with decreased expression of Notch2 could be used to facilitate the early detection of colorectal cancer." (PMID 31296250, 2019). "In colorectal cancer, EGCG induces the inhibition of cell proliferation via inhibiting the expression of transcription factor HES1 and neurogenic locus notch homolog protein 2 (Notch2)." (PMID 28587155, 2017). "MiR-195-5p was reported to inhibit NOTCH2 expression and activation in a post-transcriptional manner, leading to the down-regulation of NOTCH2/GATA3-mediated IL-4 secretion in colorectal cancer cells, ultimately suppressing M2-like TAM polarization and tumor progression." (PMID 35996149, 2022).
chronic lymphocytic leukemia (25 papers, 2011 to 2026). "In humans, NOTCH1 and NOTCH2 function as recurrently mutated oncogenes in B cell lymphoproliferative disorders, including chronic lymphocytic leukemia and MZ lymphoma." (PMID 35579963, 2022). "Members of Notch2 pathway have been reported to be mutated in Chronic Lymphocytic Leukemia (CLL), Splenic Marginal Zone Lymphoma (SMZL) and Nodal Marginal Zone Lymphoma (NMZL)." (PMID 36686759, 2022). "Notch2 overexpression is implicated in the development of chronic B-cell lymphoid leukemias, since B-cells are able to survive significantly longer than normal cells." (PMID 23599800, 2013). "Constitutively active NOTCH2 signaling is a hallmark in chronic lymphocytic leukemia (CLL)." (PMID 39684291, 2024). "Moreover, the NOTCH2 mutations identified in lymphoid malignancies (acute T-cell lymphocytic leukemia, chronic lymphocytic leukemia, SMZLs, and DLBCLs) are all gain-of-function mutations." (PMID 25314575, 2014). "Bidirectional regulation between Notch2 and N-cadherin was reported in the context of chronic lymphocytic leukemia (CLL)." (PMID 37255594, 2023). "In chronic lymphocytic leukaemia (CLL), recurrent NOTCH1 mutations were observed at all disease stages, whereas mutations in the paralogs NOTCH2, NOTCH3 and NOTCH4 were rare events with frequencies <1% (NOTCH2 in 0.9%; NOTCH3 in 0.7%; NOTCH4 in 0.6%)." (PMID 36313682, 2022). "Hyperactive Notch1 and Notch2 have been shown to sustain B cell Chronic lymphocytic leukemia (B-CLL)." (PMID 34394130, 2021). "Notch 1, Notch 2 and their ligands Jag1 and Jag2 are constitutively expressed in B-cell chronic lymphocytic leukemia (CLL) and confer resistance to apoptosis in malignant B-cells." (PMID 33374160, 2020). "Notch2 may also play an indirect role in chronic B-cell lymphocytic leukemia (B-CLL) through upregulated expression of CD23." (PMID 22128846, 2011). "In B-cell chronic lymphocytic leukemia (B-CLL), NOTCH1, NOTCH2, and their ligands (JAG1 and JAG2) are constitutively expressed." (PMID 35335147, 2022). "Genetic aberrations in Notch1 and Notch2 arise in B-cell neoplastic diseases such as Hodgkin lymphoma (HL), diffuse large B-cell lymphoma (DLBCL), chronic lymphocytic leukemia (CLL), follicular lymphoma (FL), and mantle cell lymphoma (MCL)." (PMID 31652497, 2019). "Expression of Notch2 is necessary for marginal zone B-cell development and is related to CD23 overexpression in chronic B-cell lymphoid leukemia." (PMID 23599800, 2013). "To address how NOTCH-mutations contribute to a dismal prognosis, we have generated isogenic primary human tumor cells from patients with Chronic Lymphocytic Leukemia (CLL) and Mantle Cell Lymphoma (MCL), differing only in their expression of the intracellular domain (ICD) of NOTCH1 or NOTCH2." (PMID 36266281, 2022). "Both NOTCH1 and NOTCH2 are constitutively activated in B-cell CLL but not expressed in normal B cells and may be involved in survival and resistance to apoptosis in CLL." (PMID 23734977, 2013). "Rosati E and co-workers demonstrated a high expression of Notch 1, Notch 2, JAG1 and JAG2, in malignant B-cells isolated from 25 patients affected by B-cell chronic lymphocytic leukemia (B-CLL) but not in normal B-cells." (PMID 33374160, 2020).
glioblastoma (25 papers, 2011 to 2025). The most malignant astrocytic tumor (WHO grade IV). "In cancer biology, midkine has been implicated in tumor progression in glioblastoma and neuroblastoma through ALK/NF-κB and Notch2/Hes1 signaling pathways." (PMID 41339619, 2025). "Although miR-181a downregulates Notch2 expression, miR-181a itself is downregulated in GSCs derived from U87 and U373 human glioblastoma cells." (PMID 39851559, 2025). "In glioblastoma stem cells, Notch2 further amplifies RET by interacting with complex I subunits, lowering the NAD+/NADH ratio and sustaining proliferation through SIRT1-dependent signaling; pharmacological inhibition of this RET suppresses tumor growth." (PMID 41007285, 2025). "One of the direct processes regulated by miR-34a in glioblastoma cells is considered to inhibit the expression of genes of the proteins Notch homolog 1 (Notch1) and Notch homolog 2 (Notch2), which act as transmembrane receptors." (PMID 36834933, 2023). "NAC, a GSH precursor has shown promise of inhibiting proliferation, growth, invasion, and migration of glioblastoma cells, as well as of inducing apoptosis by dowregulating neurogenic locus notch homolog protein 2 (Notch2) signaling pathways." (PMID 36307808, 2022). "In this review, we examined the contrasting activity of Notch1 and Notch2 and the signaling cascade that each generates in the angiogenesis of glioblastoma, the most invasive cancer of the central nervous system." (PMID 36643842, 2021). "In Glioblastoma tissue, astrocyte fate genes, stemness genes and anti‐apoptotic proteins are correlated with the expression level of Notch2 gene." (PMID 33047886, 2020). "This is supported by the depletion of CTCF in glioblastoma cells affecting the expression levels of NOTCH2 as a target of miR-181c." (PMID 26983574, 2016). "In the present study we observed that CTCF knockdown induces overexpression of NOTCH2 gene in U87MG glioblastoma cells possibly as a consequence of the epigenetic silencing by DNA methylation of miR-181c." (PMID 26983574, 2016). "NOTCH2 is one of the receptors of the Notch pathway and was recently shown to be important for proliferation, invasion and self-renewal of glioblastoma U87MG cells." (PMID 26983574, 2016). "The NOTCH2 gene is also a post-transcriptionally target of miR-181c and a negative correlation between NOTCH2 gene expression and miR-181c was found in glioblastoma samples." (PMID 26983574, 2016). "N-acetylcysteine (NAC) inhibits glioblastoma cell proliferation, migration, and invasion and promotes Notch2 degradation, possibly through an Itch-dependent lysosomal pathway, while decreasing mRNA and protein levels of its downstream target genes, Hes1 and Hey1, thereby inducing apoptosis." (PMID 38672496, 2024). "The miR-34a targets Notch1 and Notch2 in glioblastoma and medulloblastoma." (PMID 28073349, 2017). "Therefore CTCF loss causes the epigenetic silencing of miR-181c by DNA methylation and the inability of the miR-181c to diminish the levels of NOTCH2 transcripts in glioblastoma U87MG cells." (PMID 26983574, 2016). "Among the four Notch paralogs, Notch-2 is highly expressed in glioblastomas and may have a predominant role in glioblastoma cell growth." (PMID 22330721, 2012). "In glioblastoma, LINC01410 acts as a sponge for miR-506-3p, thereby promoting NOTCH2 expression and activating the Notch pathway, which stimulates GBM cell proliferation and inhibits apoptosis." (PMID 41472748, 2025). "On the contrary, several groups reported a weak expression of Notch1, Notch2, MAML1, and p300 in Glioblastoma." (PMID 30832246, 2019). "Concerning glioblastoma (GBM), it has been reported that transient transfection of miR-34a mimics into glioma and medulloblastoma cell lines remarkably inhibits cell proliferation, invasion, survival, and cell cycle progression by targeting c-Met, Notch-1, and Notch-2." (PMID 32083078, 2020).
bladder cancer (24 papers, 2017 to 2025). "We demonstrated for the first time direct interactions between DLL4 and Notch2/3 associated to activation of canonical downstream Notch signaling and increased tumor cell behavior in human bladder cancer cells." (PMID 39951484, 2025). "Other potentially clinically relevant genes with single base somatic mutations include NOTCH2, recently proposed as an oncogene in bladder cancer, with the Notch family pathway implicated in prostate tumorigenesis, and CNTN6 within the 3p26 prostate cancer susceptibility locus." (PMID 28423598, 2017). "The efficacy of the NOTCH2 inactivating antibody NRR2Mab has been demonstrated in preclinical model of bladder cancer." (PMID 41008920, 2025). "circKIF4A (hsa_circ_0007255) is an example of circRNAs contributing to the development and progression of bladder cancer through modulating NOTCH 2 expression." (PMID 40761890, 2025). "In 2016, Hayashi and colleagues investigated the role of NOTCH2 in bladder cancer, especially regarding its involvement in epithelial–mesenchymal transition (EMT)." (PMID 41008920, 2025). "CircKIF4A sponged miR-375/1231 accelerates tumor progression via up-regulating NOTCH2 expression in bladder cancer." (PMID 36098705, 2022). "NOTCH2 SNVs have been seen in many cancers, including diffuse large B cell lymphoma, marginal zone lymphoma and bladder cancer, where NOTCH2 can function as an oncogene or a tumor suppressor gene (COSMIC, accessed 9-Jul-2019)." (PMID 33556121, 2021). "ARAP1-AS1 was reported to sponge miR-4735-3p and upregulate the target gene (NOTCH2) of miR-4735-3p, thereby promoting bladder cancer progression." (PMID 34516333, 2021). "NOTCH2 has been found to be a robust oncogene in bladder cancer by promoting cell proliferation and metastasis through epithelial-to-mesenchymal transition, cell cycle progression, and maintenance of stemness." (PMID 32457613, 2020). "The results revealed that circKIF4A sponges miR-375/1231 to promote bladder cancer progression by upregulating NOTCH2." (PMID 32457613, 2020). "Although influential studies by Rampias and Maraver reported NOTCH1 and NOTCH2 mutations in bladder cancer, NOTCH3 was not studied." (PMID 41008920, 2025). "Our data support the view that the Notch2/3-DLL4 axis plays an oncogenic role in bladder cancer." (PMID 39951484, 2025). "Interestingly, two recent manuscripts evidenced that NOTCH2 gene alterations correlate with immune infiltration and response to therapy in bladder cancer." (PMID 41008920, 2025). "This supports the oncogenic role of the NOTCH2/NOTCH3/DLL4 axis in bladder cancer." (PMID 41008920, 2025). "Additionally, NOTCH2 was proven to be a robust oncogene in bladder cancer by activating the Notch signaling pathway." (PMID 32457613, 2020). "In our study, NOTCH2 was confirmed to be the co-target of miR-375 and miR-1231 in bladder cancer." (PMID 32457613, 2020). "For example, CHIR upregulates both β-catenin and Notch3 proteins in non-small lung cancer cell lines, although functional relevance of Notch3 in bladder cancer is unknown compared to Notch1 and Notch2." (PMID 29541396, 2018). "Moreover, different Notch paralogs may have different actions in cancerous transformation; for example, it has been described that NOTCH1 and NOTCH3 have disparate roles from NOTCH2 in bladder cancer." (PMID 28915655, 2017). "Further in vitro data correlates DLL4 protein not only with NOTCH2 but also with NOTCH3 receptor, as analysed in different bladder cancer cell lines." (PMID 41008920, 2025). "NOTCH1, NOTCH2 and NOTCH4 were significantly downregulated in bladder cancer samples compared with controls." (PMID 37728427, 2023). "In addition, Ago2-related RIP assays revealed that circKIF4A, NOTCH2 and miR-375/1231 were enriched for Ago2 in RT-112 and BIU-87 bladder cancer cells." (PMID 32457613, 2020).
bladder cancer (continued). "Further investigation revealed that METTL3/miR-146a-5p/NUMB/NOTCH2 signaling was positively correlated with recurrence, metastasis, and survival in bladder cancer patients, indicating that MLT sheds new light on therapeutic targets for recurrent bladder cancer treatment." (PMID 38017537, 2023).
melanoma (24 papers, 2015 to 2025). A malignant, usually aggressive tumor composed of atypical, neoplastic melanocytes. "Our data show that loss of Notch 1 or Notch2 cannot substitute for the tumor suppressor functions of Pten in BRAFV600E-induced melanoma." (PMID 36672468, 2023). "Taking together, this work shows that targeting canonical NOTCH2/CSL signaling by gliotoxin is associated with the induction of apoptosis in cell lines derived from melanoma, HCC, and pancreas-CA whereas the GSI DAPT is ineffective." (PMID 28736522, 2017). "e., the loss of Notch1 or Notch 2 or both fail to induce melanoma in BRAFCA mice." (PMID 36672468, 2023). "Therefore, we conclude that gliotoxin is highly active in this melanoma xenograft mouse model and, thus, is therapeutically relevant for NOTCH2 associated malignancies." (PMID 28736522, 2017). "On the other hand, a tumor suppressor role for Notch1 and Notch2 was reported in a BRAFV600E/Ptennull transgenic model of mouse melanoma." (PMID 40574005, 2025). "LncRNA-BANCR (BRAF-activated long noncoding RNA) participates in the occurrence and development of melanoma by reducing the interaction with miR-204 and activating the Notch2 signaling pathway and promotes its expression in melanoma tissues and cell lines." (PMID 36601121, 2022). "Honokiol potently inhibits melanoma cell metastasis, in part, through the targeting of melanoma stem cells by suppressing Notch-2 signaling." (PMID 30587839, 2018). "Of note is the large number of down-regulated UV-miRNAs that are connected to the melanoma gene NOTCH2." (PMID 27149382, 2016). "We found that treatment of melanoma cells with SCH984 led to decreased Notch2 and Notch3 mRNA levels in responder cells, whereas Notch3 mRNA levels were not affected in the non-responder cells." (PMID 27655717, 2016). "Of significance are the melanoma-related genes NOTCH1, NOTCH2, WNT3a, and WNT5a, each of which are associated with two or more UV-miRNAs that can directly target these respective genes." (PMID 27149382, 2016). "Anti-Notch1 selectively inhibited Notch1 but not Notch2; caused significant melanoma cell death in vitro but did not affect normal melanocytes." (PMID 39491031, 2024). "Of note, most co-occurring mutations in melanoma BRAF Class 2 and 3 (KMT2A, NOTCH1, APC) are of unknown significance, whereas those in Class 1 are amplifications and putative drivers such as NOTCH2 and MET amplifications." (PMID 38275886, 2024). "Comparative analyses of common melanocytic nevi, dysplastic nevi, and melanomas have demonstrated an increased expression of Notch1, Notch2, and their ligands, indicating that a positive regulation of these components can be related to the melanoma progression." (PMID 30166456, 2018). "In this study, we investigated the role of Notch signaling in melanoma tumor development and growth using the genetic model of mouse melanoma by crossing BRAFCA/+/Pten+/+/Tyr-CreER+ (B) and BRAFCA/+/Pten-/-/Tyr-CreER + (BP) mice with Notch1 or Notch2 floxed allele mice." (PMID 36672468, 2023). "To assess Notch1 and Notch2 activity, we used SNAP23 and BCAT2, two downstream targets of Notch1 and 2, respectively, that we identified by a microarray analysis of human melanoma cells in which each Notch receptor was inhibited by a specific shRNA." (PMID 39491031, 2024). "The high expression of NOTCH2 and USP8 has been correlated to a worse prognosis in many tumor types, including SCC, and melanoma." (PMID 39456581, 2024). "In macrophages, in vitro models of melanoma show a higher correlation of NOTCH1, NOTCH2, and Hes1 expression in M1 macrophages." (PMID 37893184, 2023). "Using that approach, the proteomic comparison of melanoma-derived plasma exosomes with remaining non-melanoma plasma exosomes showed an increase in signaling and immune regulating proteins including LDHA, NOTCH2 and thrombospondin-1 among others." (PMID 36704194, 2022).